DNASE1 (deoxyribonuclease 1)
Description:
Serum endocuclease secreted into body fluids by a wide variety of exocrine and endocrine organs. Expressed by non-hematopoietic tissues and preferentially cleaves protein-free DNA (By similarity). Among other functions, seems to be involved in cell death by apoptosis. Binds specifically to G-actin and blocks actin polymerization (By similarity). Together with DNASE1L3, plays a key role in degrading neutrophil extracellular traps (NETs) (By similarity). NETs are mainly composed of DNA fibers and are released by neutrophils to bind pathogens during inflammation (By similarity). Degradation of intravascular NETs by DNASE1 and DNASE1L3 is required to prevent formation of clots that obstruct blood vessels and cause organ damage following inflammation (By similarity).
Synonyms: DNL1; DRNI
Tractability: Antibody: UniProt places it where antibodies can reach, with high confidence; its Gene Ontology location is reachable by antibodies, with high confidence; UniProt predicts a signal peptide or a membrane-spanning region. PROTAC: a small molecule that binds it is known.
Target class: Enzyme; Hydrolase
Gene: Protein-coding gene on chromosome 16 (3,611,728 to 3,680,143, forward strand). Ensembl gene ENSG00000213918.
Subcellular location: Secreted; Zymogen granule; Nucleus envelope
Subcellular location (Human Protein Atlas): Vesicles; Predicted to be secreted
Gene Ontology:
Molecular function: deoxyribonuclease I activity; protein binding; DNA binding; catalytic activity; DNA nuclease activity
Biological process: DNA catabolic process; neutrophil activation involved in immune response; regulation of acute inflammatory response; regulation of neutrophil mediated cytotoxicity
Cellular component: extracellular exosome; extracellular region; nucleus; nuclear envelope; zymogen granule
Genetic constraint (gnomAD): Loss-of-function variants: 41 observed, 36.43 expected, observed/expected ratio (o/e) 1.13, 90% interval 0.88 to 1.46. The synonymous counts are far from expectation, so gnomAD's model fits this gene poorly and the ratio says little. Missense variants: 518 observed, 391.11 expected, observed/expected ratio (o/e) 1.32, 90% interval 1.23 to 1.42. Synonymous variants: 216 observed, 168.9 expected, observed/expected ratio (o/e) 1.28, 90% interval 1.14 to 1.43.
Gene-disease validity (ClinGen):
ClinGen rates the evidence that DNASE1 causes each of these diseases.
systemic lupus erythematosus (autosomal dominant): Limited. An autoimmune multi-organ disease typically associated with vasculopathy and autoantibody production.
Homologues: Orthologues: chimpanzee DNASE1 (99% identical), macaque DNASE1 (94% identical), dog DNASE1 (82% identical), rabbit DNASE1 (80% identical), mouse Dnase1 (79% identical), pig DNASE1 (79% identical), rat Dnase1 (78% identical), zebrafish dnase1 (54% identical), tropical clawed frog dnase1l2 (52% identical). Paralogues in human: DNASE1L2 (54% identical), DNASE1L3 (45% identical), DNASE1L1 (37% identical).
Diseases named in the same sentence as DNASE1 in open-access papers:
DNASE1 is named in the same sentence as 130 diseases in open-access papers, as found by Europe PMC text mining. Sharing a sentence is not in itself a finding about the gene and the disease. The quoted sentences say what the papers report.
cystic fibrosis (54 papers, 2006 to 2026). Autosomal recessive disorder caused by pathogenic variants in the CFTR gene (cystic fibrosis transmembrane conductance regulator), which encodes a chloride and bicarbonate channel expressed in epithelial cells, and follow the diagnosis criteria. "Recombinant human DNase1 (dornase alfa, Pulmozyme, Roche) is marketed for the treatment of cystic fibrosis patients." (PMID 37287977, 2023). "The enzymatic activity of nucleases such as Dnase1 and Dnase1L3 are particularly important in diseases such as cystic fibrosis." (PMID 35974043, 2022). "Dnase1 gene is related to DNA repairing, and Dnase I is used to treat AD neuropathologies, cystic fibrosis, and cancer." (PMID 36614117, 2022). "Deoxyribonuclease 1 or dornase alfa (Pulmozyme®) is an inhaled potent inhibitor of bacterial DNA used in patients with cystic fibrosis." (PMID 29197958, 2017). "Clinical trials have invested the use of DNase1 in humans for the treatment of cystic fibrosis, among other diseases, and thus these drugs may be clinically available for other species in the future." (PMID 39794955, 2024). "In patients with cystic fibrosis, DNase 1 (dornase alfa) is given by a nebulized route." (PMID 28935869, 2017). "Dornase alfa is a recombinant DNase 1 used as a mucolytic agent in the treatment and management of cystic fibrosis in conjunction with standard therapies." (PMID 34421600, 2021). "Dornase alfa is a FDA-approved recombinant human DNAse 1 for the treatment of cystic fibrosis, which cleaves extracellular DNA and may break up cell-free DNA, loosening sticky mucus in the distal airways and reducing NETs-induced toxicity on alveolar pneumocytes." (PMID 32560746, 2020). "Consequently, native Dnase1 as a therapy for cystic fibrosis pulmonary sputum fluidization is limited." (PMID 35974043, 2022). "Therefore, a specially constructed human recombinant DNase1, whose actin binding site is missing was developed to dissociate DNA bundles in the airways of cystic fibrosis patients; however, this DNase1 is not suitable to disassemble actin bundles due to the fact that it does not react with actin." (PMID 23189180, 2012).
lupus (38 papers, 2006 to 2025). "Deficiencies in two endonucleases that specifically target DNA, Dnase1 and Dnase1l3, are associated with systemic lupus erythematosus (SLE)." (PMID 38255187, 2023). "Supporting a role of DNases in autoimmunity, deficiency in DNase1 or DNase1L3 triggers lupus-like symptoms in ANA-positive glomerulonephritis and promotes kidney deposition of immune complexes and complement factor C3 in genetically modified mice." (PMID 37287977, 2023). "For instance, we know about the existence of cases of systemic lupus erythematosus caused by monogenic mutations in the C1qA, B, C, C1R, DNASE1, DNASE1L3, and ACP5 genes, among many other predisposing genetic variations." (PMID 36900420, 2023). "A disease associated with deficiencies of Dnase1 and Dnase1l3 in mouse is systemic lupus erythematosus (SLE)." (PMID 38255187, 2023). "Altogether, those data indicate that impaired clearance of chromatin is pathogenic due to loss of tolerance and suggest that low DNase1 activity is involved in lupus pathogenesis by favoring anti-chromatin autoantibody production." (PMID 33746957, 2021). "DNase1-deficient mice on a lupus-prone genetic background develop a SLE-like disease with production of anti-nuclear antibodies, immune complex deposition in kidneys leading to glomerulonephritis." (PMID 33746957, 2021). "Mice deficient in either DNase1 or DNase1L3 expression develop features similar to other mouse models of lupus." (PMID 29922296, 2018). "All these findings are consistent with the demonstration that mice deficient in DNASE1 develop a lupus-like phenotype." (PMID 30459768, 2018). "Deficiency in DNase1 and the resulting difficulty of removing DNA from nuclear antigens promote susceptibility to immune disorders such as systemic lupus erythematosus (SLE), Sjogren's disease, and thyroid autoimmunity." (PMID 22701800, 2012). "Patients harboring mutations in DNASE1 are at higher risk of developing lupus." (PMID 35852866, 2022). "Similarly, the loss of DNase1 or DNase1L3 in mice is associated with a lupus‐like pathology." (PMID 36098213, 2022). "Additionally, DNase inhibitory antibodies were detected in sera of lupus patients that could cause decreased DNase1 activities." (PMID 33746957, 2021). "Recently, a novel bioenzyme with dual DNase1/DNase1L3 activity has shown significant effects in murine lupus models, effectively suppressing autoantibody production and resisting neutralization by autoantibodies in SLE patients." (PMID 41209000, 2025). "We sought to re-examine the importance of DNA clearance in the pathogenesis of lupus by engineering a long-acting, bioavailable, glycopolished enzyme biologic with dual DNASE1/DNASE1L3 activity for use in murine models of lupus." (PMID 38888971, 2024). "In addition, mutations in, the gene encoding for DNaseI (DNASE1) could also cause a reduction in the levels of plasma DNaseI in a subset of BC patients, as occurs for some patients with systemic lupus erythematosus who develop lupus nephritis, a fact that should be addressed in future studies." (PMID 37275882, 2023). "Deoxyribonuclease 1 (DNase1) is a major serum nuclease whose activity is decreased in mouse and human lupus." (PMID 33746957, 2021). "The majority of published studies indicate a suppressive function of DNase1 on anti-nuclear autoimmunity, which is typical for Systemic Lupus Erythematosus (SLE) and Lupus-nephritis, the most severe complication of SLE." (PMID 34329318, 2021). "Recently, a significant number of genes have been implicated in monogenic lupus, such as several complement deficiencies, ACP5, DNASE1, DNASE1L3, PRKCD, RAG2 genes, etc.." (PMID 34796153, 2021). "Loss-of-function DNASE1 mutations and lowered DNASE1 expression in diseased kidneys of both individuals with SLE and lupus-prone mice have been described." (PMID 25147296, 2014). "The data, however, suggest that eliminating Dnase1 contributes to the acceleration of renal disease in lupus-prone mice." (PMID 20856893, 2010).
lupus (continued). "Furthermore, the relevance of DNASE1 in systemic lupus erythematosus (SLE) has been thoroughly investigated, revealing its involvement in autoimmune diseases." (PMID 38618458, 2024). "Notably, we found that the biologic prevented the development of lupus in Dnase1–/–Dnase1L3–/– double-knockout mice and rescued animals from death in pristane-induced lupus." (PMID 38888971, 2024). "Indeed, short‐term treatment with recombinant human DNase1 was found to be safe and well tolerated in a clinical trial involving patients with lupus." (PMID 36098213, 2022). "Indeed, DNase1 activity was found to be substantially lower in patients with systemic lupus erythematosus (SLE)." (PMID 39697489, 2022). "Moreover, impairment of NETs degradation due to circulating DNase1 inhibitors, or physical protection of NETs has been found in systemic lupus erythematosus (SLE) patients." (PMID 23110185, 2012). "Rare and potentially pathogenic variants in the lupus associating genes C1s, C2, DNASE1 and DNASE1L3 as well as CFHR4 were discovered in Cases 4–6 diagnosed with early-onset SLE in the present series." (PMID 35964089, 2022). "Furthermore, to evaluate whether changes in Dnase1 expression could also be involved in the progression of the human variant of lupus nephritis, renal Dnase1 expression was also assayed in biopsies from SLE patients and correlated with morphological and immune electron microscopy findings." (PMID 20856893, 2010). "There is strong evidence for a role of DNase I in SLE with DNase activity low in SLE patients and SLE-prone mice, and Dnase1-/- mice developing a spontaneous lupus-like phenotype." (PMID 16606442, 2006). "The constellation of findings supports the notion that DNASE1 and DNASE1L3 activity is a protective mechanism for the development of autoimmunity in lupus." (PMID 38888971, 2024). "An enzyme biologic with dual-acting DNASE1/DNASE1L3 activity prevents autoimmunity and death in lupus models, with implications for other diseases characterized by aberrant DNA accumulation." (PMID 38888971, 2024). "Our final murine studies examined the relative contributions of DNASE1 and DNASE1L3 to mortality present in the pristane-induced lupus model, conclusively demonstrating that DNASE1L3 activity drives this phenotype." (PMID 38888971, 2024). "However, DNase1 activity is decreased in SLE patients and inversely correlates with disease activity, e.g., lupus nephritis or levels of anti-nucleosome autoantibodies." (PMID 33746957, 2021). "Reduction in renal Dnase1 expression and activity is limited to mice and SLE patients with signs of membranoproliferative nephritis, and may be a critical event in the development of severe forms of lupus nephritis." (PMID 20856893, 2010). "We crossed Dnase1L3–/– mice with Dnase1–/– mice to generate Dnase1–/–Dnase1L3–/– double-knockout (DKO) mice on a C57BL/6 background to develop a genetic lupus murine model lacking both DNASE1 and DNASE1L3." (PMID 38888971, 2024). "The DNase1/Trap1-KO mice used in the present study do not develop lupus on the pure C57BL/6 genetic background, but develop the disease on the mixed 129 × C57BL/6 F2 genetic background, indicating that other genetic factors contribute to lupus." (PMID 33746957, 2021). "Reduced serum Dnase1 activity is a common finding in SLE patients and lupus-prone mice." (PMID 20856893, 2010). "Attempts at Dnase1 enzyme replacement therapy in mice and SLE patients have been largely disappointing, as has experimental over-expression of Dnase1 in T-cells in lupus-prone mice." (PMID 20856893, 2010).
Sepsis (18 papers, 2017 to 2025). Sepsis is defined as life-threatening organ dysfunction caused by a dysregulated host response to infection. "Another potential explanation for the accumulation of NETs and the reduction of ROS is that the loss of DNase1 and DNase1L3 impairs their protective impact on the pathogens during sepsis." (PMID 38612596, 2024). "To further confirm the mechanism by which FTB mitigates sepsis-associated coagulopathies, we used the NETs inhibitor DNase1 and the PAD4 inhibitor Cl-amidine." (PMID 36408247, 2022). "DNase1 and DNase1L3 play pivotal roles in the regulation of DNase activity in plasma, crucial for maintaining the integrity of blood and tissues during sepsis." (PMID 38454482, 2024). "Two days post-induction, DNase1/1L3-DKO mice exhibited the highest levels of circulating free DNA (cfDNA) compared to all other groups across all three sepsis models." (PMID 38612596, 2024). "There was a significant increase in DNase1 expression in wild-type mice exposed to all three types of sepsis, compared to the controls." (PMID 38612596, 2024). "The results showed that using NETs and PAD4 inhibitors had a therapeutic effect on septic rats and improved coagulation dysfunction in septic rats, consistent with previous reports that DNase1 and Cl-amidine have therapeutic effects on sepsis." (PMID 37159591, 2023). "The effectiveness of DNase1 treatment in sepsis is complex, requiring critical timing for optimal efficacy." (PMID 38259485, 2023). "High levels of cfDNA have been suggested as a predictor of mortality in adult sepsis patients DNase1 regulates NETs by degradation of DNA fragments." (PMID 35053308, 2022). "DNase1 and DNase1-like 3 can be expressed independently, degrade NETs in sterile neutrophilemia and sepsis, provide double protection, and protect the host from the harmful effects of intravascular NETs." (PMID 33816356, 2021). "Recently, NET degradation activity of Dnase1 was further corroborated when Dnase1 was also shown to have a redundant function along with DNase1L3 in the degradation of NETs formed during sterile neutrophilia and septicemia." (PMID 31354738, 2019). "In the context of sepsis, plasma DNase1 concentrations are known to increase." (PMID 38454482, 2024). "It stands out, that for both entities of sepsis, cfDNA and DNase1 were elevated significantly." (PMID 35053308, 2022). "NET (DNase1) and PAD4 (Cl-amidine) inhibitors were used to further investigate whether FTB mitigates sepsis-associated coagulopathies by inhibiting PAD4-dependent NETs production." (PMID 36408247, 2022). "However, cfDNA increased in DNase1/1L3-DKO mice undergoing sepsis." (PMID 38612596, 2024). "In contrast to LPS and Volvulus, CLP-induced sepsis showed a decreased and increased 48 h survival in PAD4-KO and DNase1/1L3-DKO mice, when compared to WT mice, respectively." (PMID 38612596, 2024). "Under sepsis conditions, the liver, lung, and intestines of PAD4-KO mice showed a somewhat increased expression of DNase1 and DNase1L3, when compared to WT mice in response to sepsis." (PMID 38612596, 2024). "Our experiments revealed the increased expression of DNase1 and DNase1L3 in PAD4-KO, compared to WT mice, in almost all three sepsis models." (PMID 38612596, 2024). "FTB, DNase1, FTB + DNase1, Cl-amidine, and FTB + Cl-amidine treatment lowered the levels of CRP, IL-6, IL-1β, and TNF-α in rats with sepsis." (PMID 36408247, 2022). "Treatment with FTB, DNase1, FTB + DNase1, Cl-amidine, or FTB + Cl-amidine increased the survival rate of rats with sepsis." (PMID 36408247, 2022). "Subsequently, we used NETs inhibitors (DNase1) and PAD4 inhibitors (Cl-amidine) to further study the involvement of NETs and PAD4 in the anti-sepsis effect of FTB." (PMID 36408247, 2022). "This study was conducted using three distinct sepsis models in PAD4 and DNase1/1L3-DKO mice." (PMID 38612596, 2024).
Sepsis (continued). "The absence of DNase1 and DNase1L3 has been demonstrated to result in severe vascular occlusions in a sepsis model, underscoring the critical importance of controlled NETosis." (PMID 38454482, 2024). "In our study, we observed higher plasma DNase1 antigen concentrations in non-hospitalized patients compared to healthy controls, consistent with the higher plasma DNase1 concentrations observed in patients with sepsis." (PMID 38454482, 2024). "Notably, in mice lacking both DNase1 and DNase1L3, the induction of septicemia results in intravascular NET clot formation, leading to vessel occlusion and eventual mortality." (PMID 38454482, 2024).